MMP9 (matrix metallopeptidase 9)
Diseases named in the same sentence as MMP9 in open-access papers (continued):
Sharing a sentence is not in itself a finding about the gene and the disease.
infection (continued). "According to the results, infection of cells with CEES heightens the expression and activity of MMP-2 and MMP-9." (PMID 39359528, 2024). "The results showed that Vegf, Mmp9, Ang-1, Ang-2, and Et-1 were significantly upregulated after GPS infection for 48 and 72 h (p < 0.05)." (PMID 38927100, 2024). "Smoking contributed significantly to an abortive host immune response, as it promoted increased levels of MMP9 production and accelerated the destruction of the ECM during the course of infection." (PMID 40809472, 2023). "CAG:581 infection accelerated the proliferation of NMIBC organoids (p < 0.01); ECM1 and MMP9 were the most upregulated genes induced by the increased colony forming units (CFU) gradient of Eubacterium sp." (PMID 36765767, 2023). "However, the time compression of peak MMP9 production within the first 30 days in high damage conditions could contribute to more rapid tissue necrosis in the center grid cell and a less effective response to infection." (PMID 40809472, 2023). "In an in vitro model of infection using human fallopian tube explants, C. trachomatis infection induced production of MMP2 and MMP9 by infected epithelial and stromal cell populations, respectively." (PMID 37265500, 2023). "The results showed that MMP-9, COX-2 and p-NF-κB levels were significantly increased in the infection groups compared to the control group." (PMID 36341547, 2023). "At weeks 5 and 9 of infection, a significant increase in MMP-1 and MMP-9 expression was observed in the lungs of infected mice compared to uninfected control mice." (PMID 36293113, 2022). "Seven infection/inflammation-related proteins in our assay, S100A9, VIM, LGALS1, APCS, MMP9, LDHA, and CRP, were elevated in TB-PEs and the other-infectious-PEs." (PMID 35197508, 2022). "In the future, attempts should be made to verify the interaction among CEACAM1, MMP‐9, and NGAL, and to further illustrate the roles of CEACAM1 in the IS, ischemia–reperfusion injury and secondary infection in the patients and animal models." (PMID 35657334, 2022). "Especially, the gelatinases MMP-2 and MMP-9, which breakdown the extracellular matrix (ECM) components, have been displayed to be upregulated in vitro following infection with Burkholderia cenocepacia." (PMID 35113856, 2022). "A significant increase in the expression of MMP1, MMP3, MMP9, MMP12, MMP13, and MMP14, was noted in Mtb-AG infected, compared with Mtb-SC-infected rabbit lungs, at both 1 and 4 weeks post infection." (PMID 34732811, 2021). "In our studies, infection with Mtb-AG leads to the upregulation of the MMP family of genes and MMP9 protein, increasing tissue fibrosis in the rabbit lungs." (PMID 34732811, 2021). "The expression of IL-1β, IL-6, IL-8, IL-18, TNF-α, MMP-9, RANKL, TLR-2, TLR-4, TLR-6, thymic stromal lymphopoietin (TSLP), and ICAM-1 was evaluated by qPCR at 2 and 24 h after infection." (PMID 33802988, 2021). "In our previous in vitro study of E. tenella infected chicken macrophages, MMP9 expression was transiently up-regulated at 12 hpi while MMP10 and MMP17 expression was up-regulated later in the infection at 48–72 hpi (unpublished observation)." (PMID 34521339, 2021). "WT and SMARCA4 complex-depleted cells in the absence or presence of pRSV infection were assayed for SMARCA4, BRD4 and RNA Pol II binding to the proximal MMP9 promoter." (PMID 33732255, 2021). "HRV16 infection also led to a significant increase in expression of genes involved in EMT (e.g., COL1A1, MMP9, SNAI1, and ZEB2) and growth factors (e.g., ~ fourfold for EGF and FGF2, and to a lesser extent TGFB1)." (PMID 34140575, 2021). "Previous studies also demonstrated a strong interaction of plasminogen with the cell surface of pathogens during infection and the role of plasmin in activation of matrix metalloproteases MMP-1 and MMP-9." (PMID 33803235, 2021).
infection (continued). "Because of the dependence of MMP-9 induction and BBB permeability during neurologic diseases on TLR4, the role of TLR4 during VEEV TC-83 infection was examined." (PMID 33487119, 2021). "Infection with H1N1 upregulated the active and latent forms of MMP-9 in the lung and an inhibitor of MMP-2 or MMP-9 reduced in lung pathology partially." (PMID 32689931, 2020). "A majority (64/92) of NF-κB signaling pathway genes were downregulated more than 2-fold with infection, whereas only 5 of 92 were upregulated, BCL2A1, IL1B, CXCL8, MMP9, and SOD2." (PMID 33194960, 2020). "At 24 h post infection, these pericytes expressed higher levels of IL-8, TIMP-1 (tissue inhibitor of metalloproteinase-1), and RANTES, but lower levels of MMP9." (PMID 30909422, 2019). "Evaluation of the change in MMP14 expression compared to other invadopodia-activated MPPs, MMP2 and MMP9, showed a significant increase in expression of all three MMPs; however, MMP14 showed the highest increase in expression following infection." (PMID 31694343, 2019). "Mmp9-/- mice infected with CVB3 showed more severe myocardial injury, elevated the foci of infection and immune infiltrates along with increased levels of IFNβ1 and IFNγ in comparison to wild types." (PMID 31394726, 2019). "After 7 days of infection with HSV-1, the expression of MMP-2 and MMP-9 in corneal tissue was stronger than that of 0d but lower than that of 2d." (PMID 31061823, 2019). "SBCMV infection of this IBRB Tricell mixture for 96 h resulted in increased levels of IL-6, MMP9, and stem cell factor with a concomitant decrease in granulocyte-macrophage colony-stimulating factor and TNF-α." (PMID 30909422, 2019). "Here, we assayed MMP2, MMP7, MMP9, TIMP1, and TIMP2, which have previously been described to be differentially expressed after infection of the CNS." (PMID 30442185, 2018). "B16F10 cells and LL2 cells were treated with Salmonella (Multiplicity Of Infection (MOI) = 0–10) and the expression of MMP-9 in tumor cells was measured." (PMID 29857512, 2018). "Endogenous mmp2, mmp7, mmp9, DKK-1, c-myc and CCND-1 mRNA and β-catenin protein expression levels were detected in P1-infected ST cells at 24, 48, and 72 h post-infection and compared with those in uninfected cells." (PMID 29593670, 2018). "For example, MMP9 cleaves and activates interleukin-8 (IL8), a cytokine that enhances neutrophil recruitment to the site of infection." (PMID 30544510, 2018). "qRT-PCR was applied to detect miR-1303 and MMP9 expression levels in HUVECs following EV71 and CA16 infections." (PMID 30228270, 2018). "Following infection, heterophils decreased ALB and FN1, and released MMP9 to enable their translocation to the site of infection." (PMID 28623956, 2017). "Infection increased placental expression of the pro-enzyme and activated enzyme form of MMP-2 and MMP-9, thus exposing both the placenta and the amniotic membranes surrounding the fetus and placenta to degradation." (PMID 29176767, 2017). "Following infection, expression levels of the immunomodulatory cytokines C-C motif chemokine 22 (CCL22), CCL1, IL-23α, IL-3, IL-4, matrix metalloproteinase 9 (MMP9), IL-21, C-X-C motif chemokine 2 (CXCL2), and CCL2 were increased." (PMID 28507072, 2017). "Intracellular WCH-SK2WT infection induced mRNA expression of TLR2, pro-inflammatory cytokines (IL1B, IL6, and IL12) and tissue remodeling factors (MMP9)." (PMID 28083514, 2016). "The relative levels of TNF-α, IL-1β, and MMP-9 mRNA transcripts and proteins in the hearts of mice with LCME infection were significantly higher than that in the PBS-injected controls (P < 0.05 for all at all time points)." (PMID 27800490, 2016). "Intracellular infection with the S. aureus WCH-SK2WT elicited a more consistent innate immune response in comparison to intracellular S. aureus WCH-SK2SCV infection with an increased expression of IL1B, IL6, IL12, MMP9, and TLR2 at 24 h." (PMID 28083514, 2016).
infection (continued). "SBCMV infection of this IBRB Tricell mixture for 96 hours resulted in increased levels of IL-6, MMP9, and stem cell factor with a concomitant decrease in granulocyte-macrophage colony-stimulating factor and TNF-alpha." (PMID 25573478, 2015). "A role for MMP-2 and MMP-9 in spontaneous rupture of membranes in term labour and PPROM and infection has been demonstrated." (PMID 24106700, 2013). "This is consistent with other data on MMP-9, where it has been observed to be increased in spontaneous parturition, preterm labour, PROM, PPROM, and infection in amniotic fluid." (PMID 24106700, 2013). "MMP-9 gene expression was induced 38 fold in ECV and 28 fold in HBMEC at 30 h after infection (Table." (PMID 24236107, 2013). "Therefore, virus-mediated MMP-9 expression might minimize infection-related collagen IV fibrosis." (PMID 22917220, 2012). "Circulating concentrations of lymphotactin, MIP-1γ, MPO, MMP9, as well as VCAM-1, CRP, SAP, and haptoglobin were altered with Hb-infection and reduced in Hb-infected mice treated with anti-IL-7Rα M595." (PMID 23057802, 2012). "The changes in the other four genes were more complex, but also depended on the time points: At day 3 post infection, Balb/c mice produced more MMP-13 and less MMP-8, MMP-9, and TIMP-1, but this trend was reversed at three later time points." (PMID 22665968, 2012). "In this study, the expression of both MMP2 and TIMP2 increased during LX-2 activation induced by TGF-β1; however, after AdNDRG2 infection, MMP2 was enhanced while TIMP2 levels decreased compared with AdLacZ controls (MMP9 and TIMP1 were undetectable)." (PMID 22110735, 2011). "In contrast, infection with T. carassii lead to an increase of CXCb (CXCL9-11-like chemokine), CXCL8_L2 (IL-8-like chemokine) and MMP-9 gene expression and a marked increase in the number of neutrophilic granulocytes in the spleen." (PMID 20885956, 2010). "It is therefore highly probable that the inflammatory process, as reflected by the elevated concentrations of MMP-8, MMP-9 and IL-8 in the CMP-dists, protects the uterine cavity against ascending infection." (PMID 20868473, 2010). "Moreover, infection with shc-Jun versus scramble shRNA abolished PARP1 overexpression-induced expression of CyclinD1, Pcna, Mmp9 and Mmp2 genes, as well as the increase in the neointima/media ratio of balloon-injured arteries." (PMID 40744995, 2025). "Although neutrophils produce Mmp9 during infection, our previous findings demonstrated that MMP-9 expression does not increase during infection, indicating its consistent expression by neutrophils under normal conditions." (PMID 40127923, 2025). "We identified 6 hub genes (IL1R1, CD163, TLR5, LY96, MMP9, and IRAK3) and 4 target miRNAs (miR-34a-5p, miR-103-3p, miR-107, and miR-124-3p) that affect the pathophysiological processes of T2DM and CS through ion transport, immune response, and infection." (PMID 40922361, 2025). "As infection resolves and inflammation subsides, neutrophil and macrophage-mediated tissue destruction diminishes, extracellular matrix (ECM) degradation mediated by MMP-9 is reduced, and granulation tissue is allowed to stabilize." (PMID 41150817, 2025). "The raw data show that there is very low expression of il1b and mmp9 in the absence of infection in all cases, as expected from the published literature for these markers in zebrafish larvae." (PMID 39336115, 2024). "Indeed, during infection, high levels of MMP-8 and MMP-9 are present in extracellular spleen homogenates and plasma." (PMID 37669943, 2023). "Of note, the disruption in PNN formation during infection was associated with increased expression of MMP-12 and -19 but not MMP-9 or ADAMTS-4 or -5, which have been previously shown to be increased in some disorders where established PNNs are disrupted." (PMID 37496706, 2023).
infection (continued). "ABZ-treated groups and MTF-treated groups exhibited decreased MMP-9 production at both time periods post-infection, with more pronounced effects seen during the acute phase rather than the chronic phase of the infection." (PMID 37874393, 2023). "Consistent with a pro-inflammatory state, LPS-preconditioning significantly increased EPO, IFN-γ, IL-1β, KC, TNF-α, MCP-1, MIP-1α, and IFN-β levels in the lungs and pulmonary FTT infection significantly reduced IFN-γ, IFN-β, and MMP9 levels among LPS preconditioned mice." (PMID 37883420, 2023). "Furthermore, the expression of several innate immune response regulators (COX-5B, MMP-9, TRIM21, TRIM25 and TRIM26) in the PAMs were also regulated differently during the PRRSV-ADE infection." (PMID 36680075, 2022). "The results found that the levels of PCT, HBP, and MMP-9 in the CSF of those with intracranial infection were significantly higher than those of without infection." (PMID 36159580, 2022). "Elegant studies using zebrafish infection with M. marinum, have established that the 6 kDa early secretory antigenic target (ESAT-6) induces the production of matrix metalloproteinase-9 (MMP-9), activation of the epithelium, and recruitment of macrophages to the site of infection." (PMID 33868200, 2021). "It has however been suggested that clarithromycin “suppresses infection-related inflammation and reduces vascular hyper-permeability by suppressing the induction of monocyte chemoattractant protein-1 (MCP-1) and matrix metalloproteinases-9 (MMP-9)”." (PMID 34020659, 2021). "MMP-9 gene expression, secretion and activity were significantly inhibited by 1α,25(OH)2D3 irrespective of infection." (PMID 33142828, 2020). "This allows for subsequent robust spread of ZIKV inside of the seminiferous tubules and infection of its target cells in seminiferous tubules such as Sertoli cells, referred to a reservoir for ZIKV, which in turn produce MMP9 accelerating the disruption of BTB and ZIKV invasion of the testis." (PMID 32302362, 2020). "Besides, MMP9 and MMP12 were highly expressed in lung lesions in CSE-exposed mice with BCG-infection." (PMID 32973788, 2020). "Levels of PE showed a similar pattern to MMP-9, being significantly raised in CC-CF patients versus non-CF controls, demonstrating trends towards higher levels in the presence of infection and a relationship with neutrophilia." (PMID 31176670, 2020). "Our data reveal that S. aureus infection may stimulate the expression of TWIST1 which up-regulates the expression of MMP9 and MMP 13, thereby promoting the migration of macrophages toward the infection sites for scavenging S. aureus." (PMID 32595631, 2020). "By contrast, in adipocytes, no further increase of the MMP-2 and MMP-9 activity was detected for any MOI of infection." (PMID 33071987, 2020). "Besides, in the human infection context, some patients in the second stage of HAT (the neurological stage) present an increase in the expression of MMP-2 and MMP-9, correlated with the presence of parasites and leukocytes." (PMID 31597256, 2019). "We confirmed that mock infection did not induce the secretion of MMP-9, MPO or NE into the airways or the upregulation of cell surface activation marker CD64 at any time point." (PMID 31358860, 2019). "In vitro infection of murine microglia cell line (BV2) with DENV 1–4 resulted in increased expression of proinflammatory cytokines, including TNF-α, IFN-γ, IL-1β and IL-10, MCP-1, and IL-6, and of MMP-2 and MMP-9." (PMID 30984122, 2019). "When infection experiments were performed in the presence of YVAD, glyburide, or A151, the effect of B. abortus infection on MMP-9 expression, collagen deposition, and TGF-β secretion on LX-2 cells was partially reversed with respect to untreated infected cells." (PMID 32038610, 2019).
infection (continued). "The levels of mmp7 and mmp9 mRNAs in the P1 infection group did not change significantly compared to those in the mock infected group in spleens, while significantly decreased in kidneys, hearts, and livers." (PMID 29593670, 2018). "The levels of cyclin D1, mmp7 and mmp9 mRNA in livers and spleens of the P1 infection group did not change significantly, but significantly decreased in kidneys and livers compared with those in the mock infected group." (PMID 29593670, 2018). "Ultimately, the morphological examination showed no obvious pathological changes in the thalamus or lungs of control monkeys, whereas different pathological responses to EGFP-CA16 infection and EGFP-CA16 + MMP9 and EGFP-CA16 + TIMP-1 treatments were found in the thalamus and lungs." (PMID 30228270, 2018). "By comparing infection by highly lethal strain of IAV to mild strain in the mouse, we observed that MMP-9 upregulation correlates with severe pathology in infection by highly lethal IAV and that inhibiting MMP-9 partially rescues IAV-induced lung pathology." (PMID 29018444, 2017). "Similarly, changes in levels of MMP-9, E-cadherin and SNAIL were seen with infection of HEK-293 cells with BAC-KSHV infection." (PMID 27463802, 2016). "Moreover, the MMP3, MMP9 and IL1B levels were more highly stimulated by infection with the oral bacterium, Fusobacterium nucleatum, in old hGFs compared to young hGFs." (PMID 27391467, 2016). "Further, the data suggest that absence of the E1A protein does not alter MMP2 or MMP9 activity or mRNA levels during infection." (PMID 27303733, 2016). "At 24 hours post infection, pericytes expressed higher levels of IL-8, TIMP-1 (tissue inhibitor of metalloproteinase-1), and RANTES (regulated upon activation normal T cell-expressed and presumably secreted) but lower levels of MMP9." (PMID 25573478, 2015). "In fetal membranes from spontaneous preterm labour and with active infection (confirmed by pathology), silibinin treatment decreased pro-inflammatory cytokine expression and release, COX-2 gene expression and prostaglandin release, and MMP-9 gene expression." (PMID 24647589, 2014). "If MMP-9 levels increase during infection, those of TIMP-1 did not change, remaining at basal levels at all time points." (PMID 25436884, 2013). "A similar pattern was observed in the current study in WTbut not MMP-9−/− mice, as the fecal microbiota of the lattergroup had no changes in diversity following infection." (PMID 22694805, 2012). "In contrast, while Il6 and Mmp9 were significantly highly expressed in HN878-infected cells at both time points, the level of expression of Cd209g was similar at 6 hours and higher in HN878-infected BMM at 24 hours of infection." (PMID 22280836, 2012). "Moreover, MMP-9 and TIMP-1 expressions were lower in the combined H. pylori-infection and NSAID-use group than in the H. pylori-infected group (P < 0.05)." (PMID 22645431, 2012). "Levels of MMP-9 in CHD and AMN increased 4- and 8-fold, respectively, after simultaneous infection." (PMID 21266053, 2011). "Upon pulmonary challenge with Francisella, proinflammatory chemokine production by type II pneumocytes, as well as induction of matrix metalloproteinase-9 (MMP-9) and subsequent breakdown of the extracellular matrix, recruits neutrophils to the sites of infection." (PMID 22567325, 2011). "At day 6 post-infection, multiple indicators of inflammation were noted including increased levels of T-cells, elevated levels of MCP-1 and CXCL10 chemokines in the cerebral spinal fluid (CSF), traumatic brain injury markers MMP-9 and LIF in the thalamus, and activated microglia." (PMID 40005568, 2025). "Future work could aim to identify the relative TIMP/MMP balance within the triple-coculture BBB throughout the infection course, to elucidate the mechanism underlying the reduction in the secretion of MMP-9, but not MMP-3, as a result of infection." (PMID 40295794, 2024).